ORAI3 (ORAI calcium release-activated calcium modulator 3)
Diseases named in the same sentence as ORAI3 in open-access papers (continued):
Sharing a sentence is not in itself a finding about the gene and the disease.
breast carcinoma (continued). "However, detailed in vitro studies using human breast cancer cell lines with different ERα expression status show that ORAI3 expression is ERα sensitive and that ORAI3 levels are greater in ERα-positive breast cancer cell lines compared to those that are ERα-negative." (PMID 30754719, 2019). "Unlike 2-APB, LOCI directly affected ORAI1 and ORAI3 at an extracellular-facing site, rather than intervening in the STIM1–ORAI1 interaction, and blocked Ca2+ entry in Jurkat T cells and a metastatic breast cancer mouse model." (PMID 38672434, 2024). "Orai3 is selectively required in MCF-7 cells, it is a contributor in SOCE in ER+ but not in ER- breast cancer cells and silencing Orai3 results in reduced proliferation, decrease in anchorage-independent growth and decreased xenograft development in-vivo." (PMID 35163823, 2022). "Unlike in ERα positive MCF-7 breast cancer cells where Orai3 silencing reduces SOCE, the upregulation of Orai3 did not contribute to SOCE in ERα negative cells." (PMID 30935064, 2019). "Notably, the overexpression of ORAI3, rather than ORAI1, plays a predominant role in prostate cancer and breast cancer." (PMID 38672434, 2024). "In contrast to STIM1 and Orai1, Orai3 has no N-glycosylation consensus motifs; therefore, we have focused our studies in the functional role of STIM1 and Orai1 glycosylation in SOCE in the breast cancer cell types as compared to MCF10A breast epithelial cells." (PMID 36612199, 2022). "Conversely, no functional role has so far been established for Stim1 and Orai1 paralogues, that is, Stim2 and Orai2, in carcinogenesis, while Orai3 is recruited by Stim1 to activate SOCE and cell proliferation in some oestrogen receptor-negative human breast cancer lines." (PMID 25126575, 2014). "Orai3 has been reported to be highly expressed in the estrogen receptor-positive (ER+) breast cancer cell lines MCF7, ZR751, T47D, and HCC1500 as well as in luminal breast cancer tissues as compared to non-tumoral breast epithelial cells and adjacent non-cancerous tissues." (PMID 34768857, 2021). "Despite the increases in hypoxia-induced ORAI3 expression in MDA-MB-468 ERα-negative breast cancer cells, this up-regulation of ORAI3 did not bestow an ability to contribute to SOCE, which is apparent in ERα-positive MCF-7 breast cancer cells where ORAI3 silencing suppresses SOCE." (PMID 30754719, 2019).
prostate carcinoma (30 papers, 2013 to 2026). A carcinoma that arises from epithelial cells of the prostate gland. "Gaining insight into the mechanisms that drive Orai3 protein degradation can aid in developing treatments for the diseases associated with aberrant Orai3 expression, particularly pancreatic, breast, lung, and prostate cancers." (PMID 41023307, 2025). "In prostate cancer, Orai3 upregulation is associated with SOCE attenuation and formation of Orai1/Orai3 heteromers regulated by AA." (PMID 34768857, 2021). "On the other hand, in prostate cancer cells Orai3 expression has been associated with the formation of Orai1/Orai3 heteromeric channels regulated by AA and reduction in SOCE, thus leading to enhanced proliferation." (PMID 34768857, 2021). "Orai3 overexpression in prostate cancer cells is able to impair the Orai1-mediated SOCE and causes prostate cancer cell resistance." (PMID 30884858, 2019). "Third, the pharmacological profile of CRAC channels in prostate cancer cell lines and hPEC differ and siRNA based knock-down experiments indicate changed Orai3 levels are underlying the altered pharmacological profile." (PMID 24240085, 2013). "Interestingly, in breast and lung cancer cells, Orai3 was demonstrated to encode a homomeric SOCE channel whereas in prostate cancer cells Orai3 was shown to constitute a heteromeric ARC channel." (PMID 34885048, 2021). "Orai3 has been related to cancer development and poor prognosis, including prostate cancer, as well as in other conditions like vascular aging, vascular injury and pulmonary fibrosis." (PMID 41009555, 2025). "Dubois and colleagues introduced a novel channel consisting of Orai1/Orai3 heterodimer and demonstrated its role in prostate cancer cell proliferation." (PMID 35821821, 2022). "Downregulation of Orai1 decreased prostate cancer cell growth, suggesting that both isoforms Orai1 and Orai3 are indispensable to drive prostate cancer cell development." (PMID 34360783, 2021). "Several earlier studies have also reported an important role of Orai3 in G1 phase transition in breast, lung and prostate cancer cells." (PMID 34885048, 2021). "Recent evidence shows that Orai3 is up-regulated in breast, lung, and prostate cancer, and contributes to tumorigenesis." (PMID 32825277, 2020). "In particular, the expression level of Orai3 in prostate cancer biopsies is upregulated, which leads to a reduction in SOCE and enhanced Ca2+ influx mediated by arachidonic acid (AA)-activated ARC channels." (PMID 33333945, 2020). "Contrarily, another study has reported that Orai3 expression is downregulated in prostate cancer cells." (PMID 33333945, 2020). "We have previously shown that in the prostate cancer cell line LNCaP a low number of Orai3 subunits within store-operated CRAC channels alters the 2-APB response compared to Orai1-mediated currents when 50 μM was applied." (PMID 32252254, 2020). "This selective utilization of Orai3 by prostate cancer cells can partially be attributed to greater evasion of apoptotic signals closely associated with sole Orai1 functioning." (PMID 32599788, 2020). "In prostate cancer cells, it is of note that Orai3 expression is the only Orai isoform that is upregulated in comparison to healthy tissues." (PMID 33036292, 2020). "Mimicking this up-regulated Orai3 expression in PC3 prostate cancer cell lines led to an increase in characteristic ARC-mediated, store-independent Ca2+ entry, and a consequent increase in NFAT-mediated cell proliferation." (PMID 32825277, 2020). "By using mice xenograft models, it was shown that Orai3 plays a crucial role in prostate cancer development in vivo." (PMID 30935064, 2019). "In prostate cancer, it was suggested that ORAI1 is implicated in a dynamic machinery of Ca2+ remodeling between ORAI1 and ORAI3." (PMID 31010205, 2019).
prostate carcinoma (continued). "Taken together, these findings show that the Orai1/Orai3 ratio is higher in prostate cancer cells than in healthy tissue, which is consistent with the observation that Orai1 is elevated in early clinically localized cancer stage." (PMID 29951353, 2017). "A study by our group found a slightly decreased Orai3/Orai1 ratio in prostate cancer tissue compared to normal prostate tissue." (PMID 29951353, 2017). "Recent reports on Orai1 and Orai3 expression levels and function were in part controversial probably due to the heterogeneous nature of prostate cancer." (PMID 29951353, 2017). "The role of Orai3 has been extensively investigated in different types of cancer including lung, breast, and prostate cancer." (PMID 29951353, 2017). "We suggest that high mAR expression levels lead to stronger store depletion and in combination with Orai3 down-regulation to higher Ca2+ signals in prostate cancer." (PMID 24240085, 2013). "Second, mRNA expression levels of Orai3 are decreased in prostate cancer cell lines LNCaP and DU145 when compared to hPEC from healthy tissue." (PMID 24240085, 2013). "In prostate cancer, ORAI3 overexpression drives proliferation via ORAI1 and ORAI3 heteromers." (PMID 41596760, 2026). "In prostate cancer cells, the expression profile of Orai3 is still controversial." (PMID 34360783, 2021). "However, prostate cancer cells also often overexpress Orai3, an alternative Orai isoform that can be store-dependent or independent." (PMID 32575848, 2020). "Genetic silencing of STIM1/Orai1 and STIM1/Orai3 protein complexes by siRNA interference has, for example, yielded promising reductions in tumour progression and metastasis in xenograft models of breast, cervical and prostate cancer." (PMID 33036292, 2020). "In addition, in xenograft models of prostate cancer, siRNA knockdown of Orai3 dramatically reduced tumour growth." (PMID 32825277, 2020). "However, 2-APB profiles of prostate cancer cells are similar to those of concatenated channels with Orai3 subunit(s)." (PMID 32252254, 2020). "In some prostate cancers, disease progression seems to be associated with a switch from ORAI1-mediated Ca2+ influx to Ca2+ influx mediated by an ORAI1/ORAI3 heteromeric channel, due to genomic alterations in ORAI3 expression and/or tumor microenvironmental factors." (PMID 30754719, 2019). "In addition, the lipid mediator arachidonic acid (AA) promotes the store-independent interaction of Orai1 with Orai3 in prostate cancer cell lines, which leads to SOCE down-regulation and promotes cell proliferation." (PMID 30123430, 2018). "Indeed, two preclinical studies, in murine models, in breast and prostate cancers respectively have highlighted that inhibition of Orai3 impairs tumor growth and metastasis suggesting Orai3 as a useful therapeutic target in oncology." (PMID 27835593, 2016). "They proposed that remodeling of Orai1/Orai3 may constitute as an oncogenic switch in prostate cancer." (PMID 25481035, 2015). "Three lines of evidence indicate that prostate cancer cells down-regulate expression of the Orai1 homolog Orai3: First, Orai3 mRNA expression levels are significantly reduced in tumorous tissue when compared to non-tumorous tissue from prostate cancer patients." (PMID 24240085, 2013). "This change in the Orai3/ Orai1 expression dynamic created a shift from the use of the canonical Orai1-based SOCE and marks the oncogenic switch that facilitates prostate cancer tumor progression." (PMID 32599788, 2020). "The potential importance of the ORAI3/ORAI1 heteromeric channel should now be explored in basal breast cancers and TNBCs, as has been assessed in prostate cancer." (PMID 30754719, 2019). "First, application of 2-APB, which blocks currents via Orai1 and enhances currents via Orai3, resulted in stronger amplification of ICRAC in primary human prostate epithelial cells (hPECs) from healthy tissue compared to prostate cancer cells." (PMID 29951353, 2017).
prostate carcinoma (continued). "This article summarizes what is known about the dysregulation of the key molecular players involved in SOCE (STIM1, STIM2, Orai1, Orai2, and Orai3) and the negative regulator TRPM4 in prostate cancer." (PMID 29951353, 2017). "Moreover, overexpression of Orai3 enhanced the number of ARC channels together with proliferation, while apoptosis of prostate cancer cells was decreased." (PMID 34360783, 2021). "We compare expression levels of STIM1, STIM2, Orai1, Orai2 and Orai3 in tumorous and non-tumorous tissue from prostate cancer patients." (PMID 24240085, 2013). "We find a significant down-regulation of Orai3 gene expression in tumorous tissue when compared to non-tumerous tissue from prostate cancer patients and an increased Orai1:Orai3 ratio." (PMID 24240085, 2013). "Indeed, it has been reported that the relative proportions of Orai proteins are altered in prostate cancer, compared with non-cancerous tissue, with a particularly up-regulated Orai3 expression." (PMID 32825277, 2020). "Thus, high expression levels of Orai3 shape a unique pharmacological profile for SOCE and Ca2+ signaling via specific CRAC channels in prostate cancer could be manipulated by substances selective for a specific channel composition." (PMID 24240085, 2013). "Orai3 is significantly down-regulated and the decrease in Orai1:Orai3 ratio might reflect a different stoichiometry of Orai1/Orai3 subunits in CRAC channel that open the possibility for specific therapeutic targeting in prostate cancer." (PMID 24240085, 2013). "In addition, a comparison of Orai1:Orai3 gene expression ratios and electrophysiological profiles upon application of 2-APB in prostate cancer cell lines LNCaP, DU145 and hPEC support the idea of low levels of Orai3 in prostate cancer, although Orai3 is not reduced per se in cancer." (PMID 24240085, 2013). "Notably, no changes in ORAI3 gene expression levels have been detected in prostate cancer." (PMID 29951353, 2017). "We thus determined relative STIM and Orai expression levels in non-tumorous and tumorous tissue from 13 prostate cancer patients by qRT-PCR, from which 13 expressed detectable levels of STIM1, STIM2 and Orai1 and 11 detectable levels of Orai2 and Orai3." (PMID 24240085, 2013).
lung adenocarcinoma (8 papers, 2013 to 2023). A carcinoma that arises from the lung and is characterized by the presence of malignant glandular epithelial cells. "Another large cohort of lung adenocarcinoma samples (n = 200) conducted by the same research group further demonstrated the association of the Orai3 immunostaining with the aggressiveness of lung adenocarcinoma." (PMID 31252656, 2019). "In conclusion, Orai3 is associated with poor prognosis of lung adenocarcinoma and might be used as a novel prognostic marker for a chemotherapy treatment indication in early stage adenocarcinoma." (PMID 27835593, 2016). "Furthermore, we showed that Orai3 expression is also associated with ERα expression in lung adenocarcinoma such as demonstrated in breast adenocarcinoma." (PMID 27835593, 2016). "In a separate study, Orai3 immunostaining showed a correlation between overexpressed Orai3 and the aggressiveness of lung adenocarcinoma." (PMID 37259313, 2023). "In their study, ORAI3 expression was found to be higher in lung adenocarcinoma tissues when compared to adjacent normal tissue and was correlated with higher tumor grades." (PMID 36142596, 2022). "H23 is another lung adenocarcinoma cell line, in which Orai3 has been reported as a major component of SOC independently of Orai1." (PMID 34065942, 2021). "We found out, for the first time, that Orai3 expression level varies drastically in lung adenocarcinoma tissues and cell line following a platinum-based chemotherapy." (PMID 34065942, 2021). "A small cohort study on human lung adenocarcinoma (n = 60) reported that the immunostaining of Orai3 was elevated in lung cancer tissues as compared to the matched nontumorous ones, and, moreover, correlated with a high tumor grade." (PMID 31252656, 2019). "Altogether, these results provide evidence that Orai3 is overexpressed in lung adenocarcinoma and the level of its expression correlates with high tumor grade." (PMID 24058448, 2013). "Furthermore, ORAI3 was suggested as a prognostic marker of metastasis and survival in lung adenocarcinoma cell models." (PMID 36142596, 2022). "Furthermore, the Orai3 channel was recently recognized as a prognostic marker of metastasis and survival in lung adenocarcinoma." (PMID 34065942, 2021). "Thus, Orai3 that has been identified as an independent prognostic marker of survival and metastasis in lung adenocarcinoma can be also used as a future strategy in targeting CSCs subsets in CDDP resistant NSCLC tumors." (PMID 34065942, 2021). "In conclusion, Orai3 protein level constitutes an independent prognostic marker in lung adenocarcinoma, and a novel prognostic marker that could help selecting the patients with worst prognosis to be treated with adjuvant chemotherapy in resectable stage." (PMID 27835593, 2016). "Moreover, we report, for the first time, that high expression of Orai3 is an independent prognostic factor for lung adenocarcinomas." (PMID 27835593, 2016). "First, we confirmed that Orai3 is overexpressed in lung adenocarcinomas." (PMID 27835593, 2016). "Although, this compound has affected both Orai1 and Orai3 expressions, these outcomes suggest that this drug could be a promising approach for cancer lung adenocarcinoma treatment." (PMID 27835593, 2016). "Furthermore, Orai3 was identified to trigger the proliferation of lung adenocarcinoma cells." (PMID 34360783, 2021). "Immunostaining of tissues from patient cohorts with primary lung adenocarcinoma showed that platinum-based chemotherapy regimens increases the expression of Orai3, but not Orai1." (PMID 34065942, 2021). "Concerning lung cancer cells, in lung adenocarcinoma cells, a higher Orai3 expression has been reported compared to noncancerous tissue, both in cell line and in native cell samples of 200 patients." (PMID 34360783, 2021). "In this study, Orai3 was overexpressed in lung adenocarcinoma as compared to their matched non-tumour samples and was associated with tumoural aggressiveness." (PMID 27835593, 2016).
lung adenocarcinoma (continued). "Likewise, the in vitro, treatment with CDDP enhanced Orai3, but not Orai1 nor STIM1 or STIM2 expression in two lung adenocarcinoma cell lines: A549 and H23 cells." (PMID 34065942, 2021).